PXDNL (peroxidasin like)
Description:
Probable oxidoreductase (Probable). Lacks peroxidase activity. Inhibits the peroxidase activity of PXDN through its interaction. [Isoform PMR1]: Endonuclease selectively degrading some target mRNAs while they are engaged by translating ribosomes, among which albumin and beta-globin mRNAs.
Synonyms: VPO2; FLJ25471; PMR1
Tractability: Small molecule: it belongs to a druggable protein family. Antibody: UniProt places it where antibodies can reach, with high confidence; UniProt predicts a signal peptide or a membrane-spanning region; its Gene Ontology location is reachable by antibodies, with medium confidence.
Gene: Protein-coding gene on chromosome 8 (51,319,577 to 51,809,462, reverse strand). Ensembl gene ENSG00000147485.
Subcellular location: Secreted; Endoplasmic reticulum; Cell membrane; Cytoplasm (Isoform PMR1)
Subcellular location (Human Protein Atlas): Cytosol; Nucleoplasm
Gene Ontology:
Molecular function: heme binding; peroxidase activity
Biological process: hydrogen peroxide catabolic process; cellular oxidant detoxification; response to oxidative stress
Cellular component: cytosol; endoplasmic reticulum; extracellular region; plasma membrane; cytoplasm
Genetic constraint (gnomAD): Loss-of-function variants: 97 observed, 101.39 expected, observed/expected ratio (o/e) 0.96, 90% interval 0.81 to 1.13. The upper end of that interval is the gene's LOEUF score, 1.13, which puts it in group 4 of 6, group 1 being the genes least tolerant of losing a copy. Missense variants: 1,765 observed, 1,552.2 expected, observed/expected ratio (o/e) 1.14, 90% interval 1.09 to 1.18. Synonymous variants: 659 observed, 617.05 expected, observed/expected ratio (o/e) 1.07, 90% interval 1 to 1.14.
Homologues: Orthologues: chimpanzee PXDNL (99% identical), macaque PXDNL (93% identical), rabbit PXDNL (80% identical), dog PXDNL (70% identical), Drosophila melanogaster Pxn (39% identical), Caenorhabditis elegans pxn-1 (30% identical), Caenorhabditis elegans pxn-2 (29% identical), Caenorhabditis elegans C46A5.4 (22% identical), Caenorhabditis elegans K10B4.1 (20% identical), Drosophila melanogaster cysu (16% identical), Drosophila melanogaster Pxd (15% identical), Drosophila melanogaster CG4009 (13% identical). Paralogues in human: PXDN (60% identical), TPO (20% identical), EPX (19% identical), MPO (19% identical), LPO (17% identical).
Diseases named in the same sentence as PXDNL in open-access papers:
PXDNL is named in the same sentence as 12 diseases in open-access papers, as found by Europe PMC text mining. Sharing a sentence is not in itself a finding about the gene and the disease. The quoted sentences say what the papers report.
breast carcinoma (7 papers, 2022 to 2025). "High PXDNL expression is reported to have decreased overall survival or relapse-free survival in breast cancer patients." (PMID 36869083, 2023). "Based on the TCGA-BRCA dataset, we found that LOXL1, SDC1 and PXDNL were highly expressed in breast cancer while the expressions levels of FBLN1, FBLN5 and ADAMTS8 were lower than those in normal breast samples." (PMID 37056938, 2023). "For the remaining two BM genes (PXDNL and SDC1), our data indicated that high expression was associated with unfavorable prognoses in breast cancer." (PMID 37056938, 2023). "Some studies have found that PXDNL was highly expressed in breast cancer and affects the survival of patients." (PMID 36869083, 2023). "Some genes contribute a lot to the riskscore, however, their roles in breast cancer were largely unstudied, for instance, Peroxidasin like (PXDNL), ATPase phospholipid transporting 8A2 (ATP8A2) and plasminogen activator, tissue type (PLAT)." (PMID 35443644, 2022). "Although not be a CGC driver, PXDNL was found with the mutation prevalence of 6.1% in 6697 patients of breast cancer and related to breast cancer immune infiltration and poor prognosis." (PMID 40478912, 2025). "One study found a general decrease in survival in breast cancer patients with high PXDNL expression, and PXDNL could be used as a potential and independent prognostic biomarker for breast cancer." (PMID 37872487, 2023). "In order to characterize whether these genes are regulated by methylation levels, we downloaded illumina methylation 450 K beadChip data of 890 breast cancer samples from TCGA project, and 4 genes (PXDNL, SLC27A2, KLRB1 and IGHV1-12) were detected." (PMID 36869083, 2023). "Similarly, breast cancer patients with increased PXDNL (p=0.00011) and SDC1 (p<0.0001), and decreased FBLN1 (p=0.033) and ADAMTS8 (p=0.00017) expression levels tended to have shorter disease-specific survival (DSS) time." (PMID 37056938, 2023). "PXDNL, as a factor that is negatively correlated with breast cancer, has been rarely explored." (PMID 37212877, 2023). "In breast cancer, the Top 5 genes were MYC, EGFR, SRC, HSP90AB1, PXDNL, and the Top 4 genes are CGC drivers." (PMID 40478912, 2025). "In this study, BM genes with differential expression and prognostic correlation in breast cancer were selected as promising prognostic biomarkers for breast cancer, including FBLN1, FBLN5, ADAMTS8, LOXL1, SDC1 and PXDNL." (PMID 37056938, 2023). "USP41, PXDNL, and USP41 were charactered by higher expression trend in breast cancer tissue." (PMID 37212877, 2023). "In addition, PXDNL and FOXD1 were reportedly involved in breast cancer pathogenesis and were significant in predicting prognosis." (PMID 35619902, 2022).
atherosclerosis (1 paper, 2022). A disease characterized by the build-up of fatty material and calcium deposition in the arterial wall resulting in partial or complete occlusion of the arterial lumen. "Given that PXDNL is a peroxidase homolog, it can be carefully speculated that PXDNL has a similar role in lipid metabolism and atherosclerosis." (PMID 35174233, 2022).
bladder carcinoma (1 paper, 2023). "In other cancer phenotype, studies have showed that PXDNL knockdown inhibited EMT and motility of bladder carcinoma." (PMID 37212877, 2023).
cardiac arrhythmia (1 paper, 2020). Any disturbances of the normal rhythmic beating of the heart or MYOCARDIAL CONTRACTION. "The high association of PXDNL variations in patients exhibiting cardiac arrhythmias coupled with the strong expression of the protein in the ventricles (specifically the intercalated discs) suggests a link between this protein and the development of cardiac arrhythmias." (PMID 32952569, 2020).
coronary artery stenosis (1 paper, 2022). "Among other SNPs, APOA5 rs2266788 and PXDNL s80056520 showed significant associations with CAC ≥400 and coronary artery stenosis ≥70%." (PMID 35174233, 2022).
depression (1 paper, 2022). "PXDNL is reported as a susceptibility gene in patients with depression." (PMID 35619902, 2022).
tumor (5 papers, 2020 to 2023). "Up-regulated PXDNL and LINC02038 in the high-risk score group synergistically construct immunosuppressive microenvironment and promote tumor progression by impairing the cytotoxic T lymphocytes (CTLs) and inhibiting NK cell function." (PMID 36869083, 2023). "In the high-risk score group, up-regulated PXDNL and LINC02038 promote the formation of immunosuppressive microenvironment and promote tumor progression by affecting NK cells and CTL." (PMID 36869083, 2023). "The frequencies of focal CNVs on this arm were significantly different between primary tumor and metastasis, spanning PXDNL, the high expression level of PXDNL was related to poor OS in colorectal cohort (TCGA, Firehose Legacy)." (PMID 34453042, 2021). "Even more, Kaplan-Meier survival curves of progression-free survival (PFS) demonstrated inferior survival probabilities in patients with high tumor expression of PXDNL (p=0.0001) and SDC1 (p<0.0001) and low tumor expression of FBLN1 (p=0.0087), FBLN5 (p=0.026) and ADAMTS8 (p<0.0001)." (PMID 37056938, 2023). "Among TME-related prognostic signature, KLRB1, SCL27A2, PXDNL, LINC02038, IGHV1-12, IGKV1OR2-108 were directly related to tumor immunity to a certain extent, reflecting the characteristics of natural killer cells, natural killer T cells and other immune cells." (PMID 36869083, 2023). "We also detected uniquely in C3N-02671 tumor tissue two protHLAIp TAAs (CCND1 and PXDNL) and five protHLAIIp TAAs (MMP2 and CEACAM5)." (PMID 32157095, 2020). "In m6A-TSHub, a total of 184,554 and 499,369 m6A sites derived from 23 normal human tissues and 25 matched tumor samples were collected (m6A-TSDB), from which some potential patterns for the tissue-specific m6A modification sites were revealed (e.g., heart-enriched genes RYR2 and PXDNL)." (PMID 36096444, 2023).
cancer (3 papers, 2023 to 2025). A tumor composed of atypical neoplastic, often pleomorphic cells that invade other tissues. "Meanwhile, we also identified novel cancer drivers, such as PXDNL, YWHAZ and MMP9." (PMID 40478912, 2025).
infection (1 paper, 2022). The state of being infected such as from the introduction of a foreign agent such as serum, vaccine, antigenic substance or organism. "Among them, peroxidasin-like protein was detected 2, 4 and 8 weeks after infection." (PMID 35271623, 2022). "Notably, T. spiralis long-chain fatty acid transport protein 1 could be detected in the early stage of infection and peroxidasin-like protein was identified 2, 4 and 8 weeks after infection." (PMID 35271623, 2022). "Interestingly, peroxidasin-like protein was observed at all three post-infection time points." (PMID 35271623, 2022). "T. spiralis peroxidasin-like protein, peroxidasin (KRY43095.1) and WD repeat-containing protein 44 (KRY28736.1) were identified with the highest scores in the infected sera 2 weeks post infection." (PMID 35271623, 2022).
PXDNL also shares sentences with these, for which no sentence is quoted: Early Repolarization Syndrome (1 paper); gout (1); Ventricular arrhythmia (1).